CASP9 (caspase 9)
Diseases named in the same sentence as CASP9 in open-access papers (continued):
Sharing a sentence is not in itself a finding about the gene and the disease.
infection (continued). "Further, we hypothesized that E. chaffeensis regulates the anti-apoptotic Yap-GLUT1-BCL-xL axis during infection to prevent subsequent Caspase-9 and -3 activation and intrinsic apoptosis." (PMID 37530530, 2023). "In addition, SM-164 treatment resulted in decreased pro-caspase and increased levels of cleaved Caspase-9 and -3 during infection." (PMID 37594275, 2023). "Furthermore, an increase in caspase-7 and caspase-9 expression levels was identified in response to B∆tbcm infection." (PMID 38110948, 2023). "There is evidence that activation of the PI3K/Akt signaling pathway inhibits apoptosis in E. tenella host cells early in infection by reducing the expression of bad content, limiting the opening of the membrane permeability transition pore, and decreasing Caspase-9 and Caspase-3 activity." (PMID 35372563, 2022). "CASP9 is a central player in the intrinsic apoptosis pathway, and both pro-and anti-apoptotic genes influencing its activation are differentially transcribed during infection." (PMID 35573800, 2022). "We found that SCRV infection could activate the mitochondrial apoptotic pathway by the detection of the activities of the caspase-3 and caspase-9 and by flow cytometry analysis in JC-1-stained cells, respectively." (PMID 34452418, 2021). "In wt cells, MVA-infection induced strong cleavage of caspase-8, caspase-9, and caspase-3." (PMID 34711816, 2021). "With ∆M38.5/M41.1 infection, WT cells exhibited activation of CASP9, CASP7, and CASP3." (PMID 34578288, 2021). "In the later stages of infection, macrophages underwent caspase-8-independent apoptosis characterized by activation of caspase-9 and caspase-3/7, suggesting intrinsic apoptosis can also be activated during B. thailandensis infection, consistent with previous reports." (PMID 34154417, 2021). "In our study, 3D was found to suppress the apoptosis in A549 cells induced by A/Weiss/43 H1N1 in a dose-dependent manner at 24 h post-infection and repressed the expression of cleaved caspase-3, caspase-7, caspase-9, and cleaved PARP (the main cleavage target of caspase-3 in vivo)." (PMID 33670217, 2021). "PrimePCR array analysis of hNS/PCs showed that the mRNA levels of inflammatory cytokine related genes (IL-1A, TNFα, IL28A, IL29, NF-KB2), chemokines (CSF2, CCL3, CCL4, CXCR3),TLRs (TLR3, TLR8), IL-10, and Casp9 were all reduced in the Smaducin-6 treated group following ZIKV-FSS13025 infection." (PMID 32544190, 2020). "However, upon infection with Salmonella, both Gsdmd–/–;Bid–/–;Mlkl–/–;Casp3–/–;Casp7–/–;Casp9–/– and Gsdmd–/–;Bid–/–;Mlkl–/–;Casp3–/–;Casp6–/–;Casp7–/–;Casp9–/– iBMDMs underwent substantial cell death, although this was delayed compared to WT iBMDMs." (PMID 32735843, 2020). "Taken together, these data from two airway cancer cell lines and three different cytotoxicity assays indicate that scriptaid pretreatment followed by P/V-CPI- infection leads to increases in caspase-9 and -3/7 activity and to increases in cell killing through caspase-dependent pathways." (PMID 31083335, 2019). "Importantly, the infection-mediated increase in the cleaved caspase-9 level was clearly higher in PBMO than in CBMO confirming that CBMO have a reduced potential to undergo intrinsic apoptosis when compared to PBMO." (PMID 32082070, 2019). "However, the activation of caspases appeared to be opposite at the late stage of infection: at 24 hrs p.i., a lower amount of cleaved caspase-9 (p35 subunit cleaved at Asp315) and cleaved caspase-3 was observed in HAX-1kd cells than in HAX-1wt cells." (PMID 29576744, 2018). "Since HAX-1 is suppressive to apoptosis through binding to procaspase-9, an association of HAX-1 and PB1-F2 during the infection may sequester PB1-F2 from activating procaspase-9, resulting in decreased activation of caspase-9." (PMID 29576744, 2018).
infection (continued). "A gradual increase in mitochondrial cytochrome c release was observed after 1 h post-infection (p < 0.05), with significantly higher caspase-9 activation (p < 0.01) from 1 h and markedly enhanced caspase-3 (p < 0.05) activation from 3 h of infection as compared to the control group." (PMID 28573110, 2017). "Furthermore, it was demonstrated for the first time that CHIKV induces apoptosis in macrophages by both intrinsic and extrinsic pathways, as induced expression of the cleaved caspase-9 and -8 were observed during infection." (PMID 28067803, 2017). "Caspase-12, caspase-9, and caspase-3 were activated over a 48 h infection period." (PMID 28018864, 2016). "Next, the activities of caspase 8 and caspase 9 on infection with either H37Ra or H37Rv were monitored at 24 hrs of infection, using calorimetric assay, and we found that the expression level of caspase 8 was reduced to 50% (0.8 ± 0.3) in host cells infected with H37Rv." (PMID 25785198, 2015). "To address how caspase-3 is not activated by infection-induced activated caspase-9, we first analyzed expression of genes encoding inhibitors of apoptosis protein IAP1, IAP2, and XIAP." (PMID 26290316, 2015). "To determine whether intrinsic or extrinsic pathways were activated during apoptosis induced by DENV2 infection, we detected protein levels of caspase-3 and 8 using immunoblotting and anzyme activity of caspase-9 using colorimetry." (PMID 26244642, 2015). "Interestingly, we observed a significant activation of caspase 9 on day 1 post infection, while caspase 8 was shown to be activated from day 2 post infection." (PMID 24034452, 2013). "Interestingly, while caspase-9 processing was blocked, caspase-8 activity was even increased by infection with Simkania, demonstrating the selective inhibition of caspases in cells infected with Simkania." (PMID 21799887, 2011). "To determine whether apoptosis was mediated by extrinsic or intrinsic pathways we exposed lymph node cells from progressor animals taken at week 12 post infection to small molecule inhibitors of caspase-8 or caspase-9, respectively." (PMID 21203477, 2010). "Furthermore, in HCT116 PUMA-/- cells, caspase-9 activity was also increased after Ad-E2F-1 infection, albeit at a much lower level than SK-MEL-2 and HCT116 PUMA+/+ cells." (PMID 17263886, 2007). "TUNEL- and caspase-9-staining were located in alveolar macrophages at 12 h post-infection." (PMID 17257395, 2007). "Additionally, a proteomic analysis comparing lesion versus normal skin showed a positive correlation between CL and expression of caspase-9, caspase-3 and granzyme, data that corroborate cell death mechanisms with the local tissue destruction due infection by L. braziliensis." (PMID 38381750, 2024). "Interestingly, Caspase-9 is required to activate Bax, which induces apoptosis during infection." (PMID 37650558, 2023). "Indeed, after infection, we observed, with both siRNAs, a significant increase of caspase-9 (to about 1.5 fold ± 0.03 and 1.3 fold ± 0.04) and of 89 kDa PARP-1 fragment (to about 2.7fold ± 0.21 and 7.6fold ± 0.23) compared to infected scrambled cells, used as a control." (PMID 35765029, 2022). "During mono - infection (with A. salmonicida or GCRV-I) and coinfection, gcHnf4α overexpression consistently increased aif, caspase 3 and caspase 9 mRNA levels, with caspase 8 expression induced only during single-pathogen infections." (PMID 40920830, 2025). "To assess the functional role of caspase-9 in Rh-B8-induced apoptosis, we employed a selective and irreversible caspase-9 inhibitor (Z-LEHD-FMK) during infection." (PMID 40607949, 2025). "To determine the specific mechanism, we examined the levels of apoptosis-related genes (BAX, APAF-1, TNF-α, Caspase-9, Caspase-3, and BCL-2) in EBL cells following infection with M. bovis." (PMID 39308873, 2024). "Nevertheless, we found a significant reduction of caspase-9 and a significant increase of 89 kDa PARP-1 fragment after infection." (PMID 35765029, 2022).
infection (continued). "After confirming that DTMUV can activate caspase-9, we found that DTMUV infection of DEFs can promote the release of Cyt C from mitochondria to the cytoplasm and can also inhibit the expression of the antiapoptotic protein Bcl-2." (PMID 35799206, 2022). "From 12h to 72h post-infection, compared with the lean group or the DIO group, the expression levels of Caspase-3, Caspase-9 and Bax mRNA, and Bax/Bcl-2 mRNA ratio in the lean-E." (PMID 31085802, 2019). "When measuring cleaved caspase-3 in response to infection and AREG stimulation, we obtained similar results as for cleaved caspase-9." (PMID 32082070, 2019). "The activity of caspase 9 slightly increased in H1N1 and H3N2 infected cells, respectively, during the first 48 hpi, when compared with mock infection." (PMID 27042352, 2016). "The cleavage of BID and activation of caspase-9 and -3 were reduced in macrophages pretreated with the caspase-8 specific inhibitor (Z-IETD-FMK) prior to Mtb-infection compared with untreated cells." (PMID 27552917, 2016). "Two other proteins associated with cell death and apoptosis, B-cell lymphoma-extra-large (Bcl-xL) and Caspase-9, were identified as being up-regulated and down-regulated by CIV (H3N2) infection." (PMID 25883591, 2015). "Several apoptosis-related molecules such as caspase 3, caspase 8, caspase 9, and BAX appeared to be induced under conditions of reduced IFIT3, and the expression of these molecules was further enhanced by DV infection." (PMID 24223959, 2013). "Pre-treatment of macrophages with caspase-9 inhibitor Z-LEHD-FMK partially blocked caspase-3 activation and 30% remained following infection of RAW cells by WT Y. pestis." (PMID 23633954, 2013). "The delayed activation of caspase 8 (as compared to caspase 9) would also support activation of this pathway through TRAIL, which showed significant levels of expression only after 24 hours infection." (PMID 24034452, 2013). "Lung tissue sections from anti-PLY IgG-treated mice have a lower percentage of caspase-9 stained cells than PBS- (P < 0.01) and control IgG-treated mice (P < 0.05), at 48 h, 60 h and 72 h post-infection." (PMID 17257395, 2007). "Through TUNEL assay, flow cytometry, and apoptotic pathway analysis, Our analysis revealed that H5N6 AIV infection markedly upregulates apoptotic genes such as Fas, FADD, caspase-8, BAK, cytochrome c, APAF1, caspase-9, and caspase-3 (P < 0.05), thereby promoting apoptosis in DEFs." (PMID 41992349, 2026). "Moreover, at the later stages of infection, RSV induced caspase-9–mediated intrinsic apoptosis and GSDME-dependent secondary pyroptosis, thereby exacerbating cell death." (PMID 41576161, 2026). "The expression of the apoptosis marker caspase-9 was, therefore, examined by real-time qPCR during infection in the presence or absence of torin." (PMID 40042894, 2025). "In addition, PRV induced apoptosis with an increase in Bax expression and activation of caspase 9, and the phosphorylation of JNK, ERK and p38 MAPKs were significantly up-regulated in porcine ovarian granulosa cells post PRV infection." (PMID 38263223, 2024). "Meanwhile, we also found caspase-9 and caspase-3/7 activation during ASFV HLJ/18 infection." (PMID 34835046, 2021). "Measuring activities of caspases in both mammalian and mosquito cells with DENV2 infection revealed no evident activation of caspase-9 (the initial caspase) or caspase-3 (the effector caspase) in the former (C6/36 cells) at 48 hpi." (PMID 33807863, 2021). "The infection of oncoVV-WCL increased the expression of caspase-3 and cleaved caspase-9, suggesting that the intrinsic apoptotic pathway may play a role in oncoVV-WCL induced cell death." (PMID 34064193, 2021).
infection (continued). "No evident change in caspase-8 and caspase-9 occurred in cells at 48 h post-infection compared to mock-infected cells." (PMID 30670030, 2019). "This is not unique to trypanosoma infection since infection of MM cells with myxoma virus also induces activation of caspase-9." (PMID 28881710, 2017). "Generation of infectious progenies from caspase-9−/− MEFs was consistent with the infection rate as well (data not shown)." (PMID 26290316, 2015). "Treatment of IAV-infected P815 cells with VAD (pan-caspase inhibitor) and LEHD (caspase-9 inhibitor) dramatically decreased viral titers 24 h after infection, and IETD (caspase-8 inhibitor) did not." (PMID 24923273, 2014). "However, the cleaved caspase-3, caspase-9 and PARP were markedly increased in autophagy knockdown cells following MV-Edm infection." (PMID 25004098, 2014). "In the meantime, elevated (1.46-fold) caspase-9 activity appeared in IAP-knockdown and DENV-infected C6/36 cells at 48 hpi, while caspase-3 showed an increase of 1.54-fold at the same time after infection." (PMID 22530071, 2012). "An additional function of F1L has recently been reported, namely the direct inhibition of caspase-9, and this mechanism may add to the anti-apoptotic effect of MVA-infection." (PMID 21698224, 2011). "Overexpression of gcHnf4α in the case of inhibition of caspase 9 had context-specific effects: no impact during A. salmonicida mono-infection, but a significant 15%/6% decrease in survival during GCRV-II/coinfection, highlighting its specialized role in antiviral immunity." (PMID 40920830, 2025). "Sirpa and Casp9 expression did not change significantly after 4T1 medium and infection." (PMID 40547518, 2025). "While caspase 8 was not involved, caspase 9 cleavage started 24 h post-infection." (PMID 38087282, 2023). "In this study, we demonstrated that the human tonsillar epithelial cells infected with EV-A71 underwent apoptotic, in which cytochrome c was released from the mitochondria to the cytosol and caspase-9 was activated, while caspase-2 and -8 were not cleaved or activated during the infection." (PMID 33481814, 2021). "However, the levels of pro-caspase-8 were unchanged and the cleaved form of caspase-8 was never detected throughout the infection, suggesting that the infection only induced the activation of a caspase-9-dependent intrinsic apoptotic pathway." (PMID 33481814, 2021). "Intrinsic BAX/BAK-dependent apoptosis or caspase-9 cleavage has been reported following H5N1 and seasonal H1N1 infection of human primary type I-like alveolar epithelial cells, as well as PR8 infection of A549 cells, primary murine tracheal cells and H7N9-infection of human blood-derived monocytes." (PMID 32260457, 2020). "However, no activation of caspase-9 and mitochondrial release of CytC was observed during an infection, while AIF and/or EndoG showed translocation from the mitochondria to the cytosol." (PMID 29184851, 2017). "Interestingly, Chlamydia required caspase-9 activation for its infection, but this did not lead to caspase-3 activation or apoptotic events, and caspase-9 activation occured without Apaf-1." (PMID 26290316, 2015). "In order to determine the relationship between caspase-9 and caspase-3 cascade, Sl-1 cells were infected by AfMNPV in the presence or absence of caspase-9 inhibitor (Z-LEHD-FMK) and caspase-3 activities were measured by a spectrofluoremeter at 10 h post-infection." (PMID 22952575, 2012).
infection (continued). "The activation of caspase 9 in C-PA-infected cells indicates that C-PA infection induces apoptosis through the mitochondrial pathway, and the apoptosis induction by C-PA began at an early time after infection at which no apoptosis was induced by WSN infection." (PMID 22681768, 2012). "Characterizing the mechanism of cell death after infection with pathological prion protein increased caspase-9 and caspase-3 activity was detected and the lack of NF-κB activity resulted in the inability to activate target genes that usually play an important role in neuroprotection." (PMID 17573907, 2007). "The results showed that tBid-induced caspase-9 activation, as well as its cleavages of caspase-3, caspase-7, and PARP1, was blocked by CopC-positive C. violaceum but not the ΔcopC infection." (PMID 35446120, 2022). "Quantitative PCR showed VZV DNA increasing over time in HAdCCs, yet no cell death was seen at 3 days post-infection by TUNEL staining or Western Blot analysis with PARP and caspase 9 antibodies." (PMID 35458404, 2022). "Caspase-9 activity in AdBcl-xL-overexpressed cells was significantly lower than that in pCDNA3.1-flag-transfected cells and in non-transfected cells at 12, 24, and 48 h after GSIV infection." (PMID 34835028, 2021). "Further, it has recently been shown that the highly pathogenic NW arenavirus JUNV does not induce apoptosis during in vitro infection, whereas the closely related but apathogenic TCRV triggers caspase-dependent apoptosis by activating Casp9 and Casp3 cleavage at late stages of infection." (PMID 33045019, 2020). "MRC-5, MRC-9, and TIG-1 fibroblast cell death induced by live Mtb bacilli 2 days after infection was specifically inhibited by VX-765, an inhibitor of caspase-1/4, and MCC950, an inhibitor of NLRP3 inflammasome, but not by PAC-1, a caspase-3 inhibitor, and z-LEHD-fmk, a caspase-9 inhibitor." (PMID 40387341, 2025).
neurodegenerative disease (12 papers, 2015 to 2025). A disorder of the central nervous system characterized by gradual and progressive loss of neural tissue and neurologic function. "CASP9 is well-studied in neurodegenerative diseases, with increasing levels of CASP9 implicated in AD brains as well as platelet-rich plasma." (PMID 40228177, 2025). "The most well-studied context of pathological caspase-9 activation is in neurodegenerative disease, where multiple studies have reported increased expression of both total and cl-caspase-9 in apoptotic neurons, glial cells, serum and CSF." (PMID 34305609, 2021). "Exploring caspase signaling across different organ systems can help expand our understanding of degenerative diseases by examining cell-type specific dysfunction subsequent to caspase-9 activation." (PMID 34305609, 2021). "In neurodegenerative diseases, cGMP/PKG pathway inhibition activates the caspase-9/caspase-3 cascade to induce neuronal death." (PMID 40906180, 2025).